CXCL1 (C-X-C motif chemokine ligand 1)
Diseases named in the same sentence as CXCL1 in open-access papers (continued):
Sharing a sentence is not in itself a finding about the gene and the disease.
infection (continued). "Genetically altered obese/T2D (db/db) mice demonstrated increased neutrophil infiltration in infections of the hind paw and heightened production of chemokines CXCL1 and CXCL2 12 h after infection." (PMID 35315698, 2022). "Expression of macrophage and neutrophil chemoattractants CXCL10, CCL3, CXCL1 and CXCL2 in the lung tissue were significantly lower in NOX4 TG mice compared to the WT mice at 3-days post infection." (PMID 35601109, 2022). "In response to ocular HSV-1 infection, pro-inflammatory cytokines including IL-1, IL-6 and chemokines including CCL2, CCL3, CCL5, CXCL1, CXCL2, CXCL9, and CXCL10 are produced rapidly following infection by resident cells and infiltrating leukocytes." (PMID 36685562, 2022). "There was a significant increase in mRNA expression of macrophage and neutrophil chemotactic factors CXCL10, CCL3, CXCL1 (KC) and CXCL2 in the lungs of IAV-infected WT mice 3-days post infection." (PMID 35601109, 2022). "Compared with the control group, CXCL-1 in the RS218 infection group and DE205B infection group increased 8.62-fold and 5.80-fold and IL-10 increased 5.19-fold and 2.46-fold, respectively." (PMID 36143390, 2022). "CXCL1/KC and CXCL2/MIP-2 result in the recruitment of neutrophils to the lungs and subsequent viral clearance and control of the infection." (PMID 36613652, 2022). "Proinflammatory cytokines associated with Th17/Th1 response such as IL-6, TNF-α, and IL-1β, and neutrophil-recruiting chemokines including CCL2, CCL3, CXCL1, and CXCL2 were highly produced from day 3 to day 14 after WT infection." (PMID 35696422, 2022). "The infection with Pa increased NAG and MPO activities (indicative for macrophages and neutrophils, respectively) and the concentrations of CXCL-1, IL-1β, IFN-γ, and IL-10 compared to the NI group." (PMID 35548467, 2022). "Consistent with RT-PCR results, compared to the control group, the concentration of CXCL-1 and IL-10 were significantly increased in brain tissue of RS218 (p < 0.01, p < 0.001) and DE205B (p < 0.01, p < 0.01) infection groups." (PMID 36143390, 2022). "In agreement with higher local CXCL1 concentrations, Dnmt3bfl/flCc10Cre mice had higher neutrophil numbers in their BALF when compared with control mice at 6 hours after infection with PAK." (PMID 33793661, 2021). "ELISA confirmed that the increased cytokine production (CXCL1, CXCL2, IL-6, and IL-1β) induced by bacterial infection was reverted by AnxA1 treatment in WT mice at 14 h after infection." (PMID 33318141, 2021). "After infection with an influenza A virus (IAV), CXCL1, CXCL2, and neutrophils were found in lung tissues and airways of neonatal mice." (PMID 34737734, 2021). "Treatment of mice with gefitinib inhibited C. albicans-induced phosphorylation of both EphA2 and EGFR in the oral epithelial cells, and reduced the tissue levels of CXCL1/KC, CCL20, and S100A8 after both 1 and 2 days of infection." (PMID 33471869, 2021). "We demonstrated that miR‐146a inhibits the pro‐inflammatory chemokines IL‐8, CXCL1, and CCL5, induces the production of IFN‐λ, and has the capacity to limit infection by RV‐A16 in HBECs." (PMID 34185416, 2021). "Several chemokines were induced quickly in the early phase (day 2 p.i.)and maintained at a rather high level through the first week of infection, including CCL2, CCL3, CCL4, CCL7, CXCL10, IL-6, IFN-γ, CCL11, CCL5, TNF-α, CXCL1, IL-4, IL-12p70." (PMID 34379705, 2021). "Compared to sham treatment, RV-C15 infection significantly increased mRNA expression of IFN-γ, CXCL10, CXCL1, CXCL2, TNF-α, IL-12, IL-25, IL-13 and IL-5." (PMID 33968043, 2021). "Previous studies on GBS infections found that CXCL1/2 quickly increased due to GBS infections, which typically peak approximately 3-6 hours after infection." (PMID 34899755, 2021). "They demonstrated that the KO mice were defective in recruitment of CD11bHigh Ly6GHigh neutrophils, chemoattractants, and stabilizing factors like CXCL1, CXCL2, CCL3, and CSF3 to the site of infection in the colon." (PMID 34724858, 2021).
infection (continued). "Protection against lethal infection; reduced granulocyte recruitment; reduced expression of proinflammatory cytokines CXCL10, CXCL1, CCL2, and TNF." (PMID 34557097, 2021). "Downregulation of the CXCL1/2/5-CXCR2 axis, as demonstrated in the CXCL5-/- infection mouse model and the CXCR2 blockade model, enhanced CXCL13 expression in infected lungs as soon as during the innate immunity stage." (PMID 34868067, 2021). "Multiple factors contribute to neutrophil recruitment from the circulation to the site of infection, including proinflammatory cytokines (such as IL-1α, IL-1β, TNF-α, and IL-6) and Cxcr2 chemokines (such as Cxcl1, Cxcl2, Cxcl5, and Cxcl8)." (PMID 34011393, 2021). "Following in vitro infection with A/Japan/305/57, murine CD103+ DC readily produce IL-12 and CXCL1, whereas CD11b+ DC secreted CCL5." (PMID 34152253, 2021). "A common thread between our findings in the skin and those in the lung is the correlation between increased CXCL1 production with increased type I IFN signaling and increased neutrophil recruitment to the site of infection." (PMID 33690673, 2021). "In our study, cytokines, such as MIP-1α/β, RANTES/CCL5, MDC/CCL22, KC/CXCL1, and LIX/CXCL5 were upregulated after infection." (PMID 35126335, 2021). "Notably, compared with S. aureus-infected WT mice, similarly infected RBP-J CKO mice had lower percentages of splenic neutrophils at 3, 6, and 24 h post-infection, suggesting that CXCL1/CXCL2 released by MZ B cells may recruit neutrophils in the early phase of systemic S. aureus infection." (PMID 34040603, 2021). "We observed increased levels of CXCL1, CCL2 and TNF-α in the spleens of Δisp2-infected mice after 4 days of infection." (PMID 34153047, 2021). "VSV infection significantly induced the expression of seven chemokines (CCL3, CCL4, CCL5, CCL20, CXCL1, CXCL2, and CXCL3) by ~3- to 42-fold compared to mock infection." (PMID 34578166, 2021). "Therefore, the significantly reduced secretion of CXCL1 in the first and fourth weeks of infection of miR-378b−/− mice may imply a reduced number of neutrophils recruited to the site of infection of miR-378b−/− mice compared to infected WT mice, hence the reduced pathologies in the former." (PMID 34067003, 2021). "Only 4 genes overlapped both time points that also increased expression across MOIs (CXCL1, CXCL2, CXCL8 and IL6), indicating their importance as immune mediators against infection." (PMID 34001998, 2021). "PAK elicited high levels of CXCL1, CXCL5, and CCL20 in BAL fluid (BALF) at 6 hours post-infection, with lower concentrations at 24 hours." (PMID 33793661, 2021). "CXCL1 and its paralog CXCL2 have been shown to mediate neutrophil recruitment and activation to different tissues in response to infection." (PMID 34686752, 2021). "The production of CXCL1, IL-1β, TNF, and IL-6 was decreased in the lungs of Trem1−/- mice at early stages on the infection (2 dpi)." (PMID 33525982, 2021). "C. albicans GDH18 infection led to enhanced mRNA expression levels of Dectin-2, TLR2, CCL2, and CXCL1/KC, compared with the levels in uninfected mice." (PMID 33919079, 2021). "Transcriptome profile of human umbilical vein endothelial cells (HUVEC) infected in vitro with ZIKV revealed upregulation of IL-15, CCL5, HGF, LIF, M-CSF, CXCL1 and CXCL12 24 h post infection." (PMID 34357089, 2021). "At early time points of C. albicans infection, Trim31−/− mice showed significantly reduced secretion of IL-6, TNF-α, IL-12, CXCL1, and CXCL2 in their serum at 24 h post-infection as compared with Trim31+/+ mice." (PMID 34362877, 2021). "Upon experimental infection with L. major, macrophage inflammatory protein (MIP)-2 and keratinocyte-derived cytokine (KC; also known as CXCL1), the functional murine homologues of human CXCL8 are rapidly produced in the skin." (PMID 34832536, 2021).
infection (continued). "Levels of IL-1β, IL-6, CCL2, CCL3, CXCL1, and CXCL2 were significantly greater 6 h following infection than in mock-infected mice (P < 0.05) but were similar among wild-type, CCR2−/−, and Nr4a1−/− mice." (PMID 31818962, 2020). "Presently, the induction level of IL-1β, CXCL1 (KC), CXCL2 (MIP-2), and CCL2 (MCP-1) mRNA in the lungs after infection was significantly higher in klotho KO mice than in klotho WT mice." (PMID 33329595, 2020). "As mentioned, we found that the expression of CXCL1, CXCL12, CCL2, CCL5 and TIMP-1 was significantly increased upon CGS-17 and CXZ-15 infection." (PMID 33081802, 2020). "The analysis in this study revealed an increased inflammatory response, and the expression of CXCL1, CXCL12, CCL2 and CCL5 was significantly increased upon natural street RABV strain infection of dogs or humans compared to artificial mouse infection." (PMID 33081802, 2020). "Infection with P. zopfii GT-II in MEC induced early IL-1β, TNF-α and Cxcl-1 gene expression (after 2 hpi)." (PMID 31959834, 2020). "The high secretion of CXCL1 and CCL3 in ECD mice leads to the recruitment of more innate immune cells to the site of the infection increasing the possibility of having adverse pathological outcomes." (PMID 32958779, 2020). "One-week post infection, infected ECD mice produced significantly higher levels of CXCL-1 and CCL3 compared to the other groups (p < 0.0001, p < 0.01 respectively), which then decreased 2 weeks post infection." (PMID 32958779, 2020). "Then, we showed a lower level of CXCL1 and CCL3 in TLR-2KO and TLR-4KO peritoneal lavage, suggesting that TLR-2 and TLR-4 are important to chemokine production by resident cells in the infection site." (PMID 33193308, 2020). "Infection of P. zopfii GT-II in macrophages upregulated mRNA expression of IL-1β, TNF-α and Cxcl-1 (2 h)." (PMID 31959834, 2020). "Gene expression analysis revealed a subset of genes, including Csf2, Cxcl1, Fas, and Cxcl2, were upregulated during T3DPL infection independently of RIG-I and/or IFN activities." (PMID 32956403, 2020). "The genes, Ccl2, Ccl20, Csf1, Cx3cl1, Cxcl1, Cxcl3, Il6, Birc3, Map3k8, Nos2, Nfkb2, Tnfrsf1b, and Vcam1, played core roles in a PPI network, and interacted closely with other ones in the infection." (PMID 33042984, 2020). "Of note, although the serum level of IL-6, CXCL1, and CCL7 in klotho WT mice decreased at 3 days post-infection, those in klotho KO mice was maintained until 3 days post-infection." (PMID 33329595, 2020). "infection, whereas the corresponding early responding genes in SCC cells were IL10, IL1β, IL1α, TNF, CXCL10, CXCL1, HBEGF, IL6, and CSF3." (PMID 31912662, 2020). "CXCR1, and mainly CXCR2 expression, on neutrophils grants an additional form of chemotaxis away from the bone marrow via their respective ligands, CXCL1 and CXCL2, which are produced by macrophages and mast cells at the site of infection." (PMID 30791481, 2019). "To study the influence of B1R/B2R on the inflammatory response at the primary site of infection, we measured cytokine (tumor necrosis factor (TNF) α, interleukin (IL)-1β, and IL-6) and chemokine (CXCL1, CXCL2, and CCL2) levels in whole lung homogenates." (PMID 30874974, 2019). "Compared to mock infection, RSV infection via both inoculation methods resulted in increased BAL concentrations of CCL2 (MCP-1), CCL5 (RANTES), CXCL1, CXCL10 (IP10), IFN-α, IFN-γ, and TNF." (PMID 31163619, 2019). "Going well along with an improved response to infection, SIRT3/5−/− mice had significantly higher blood concentrations of TNF at day 1 (P = 0.001), TNF and IL-1β at day 2 (P = 0.004 and 0.03) and KC/CXCL1 at day 3 (P = 0.05)." (PMID 31632409, 2019). "LTB4/BLT1 axis is required for the synthesis of chemokines that recruits neutrophils (CXCL1 and CXCL2), monocytes (CCL2, CCL8, and CCL7) and T cells (CCL4) at both days 1 and 9 after infection." (PMID 30102746, 2018).
infection (continued). "This unique chemokine profile targets different populations of immune cells like dendritic cells, T cells, and B cells by CCL20, neutrophils by CXCL1 to CXCL3, and macrophages and T-cells by CCL2 to the site of infection." (PMID 29726306, 2018). "In this study, caspase-1/11 KO mice had reduced pulmonary levels of KC (CXCL1, an important neutrophil chemoattractant), and also exhibited a significantly lower number of neutrophils in BALF after infection." (PMID 30456207, 2018). "Chemokine expression analysis revealed that T3SS mutant induced lower mRNA levels of CXCL1, CXCL2, CXCL5, CXCL10 and CCL20 than the wild-type strain at 16 h post-infection." (PMID 30070169, 2018). "Conversely, CXCL‐1, CXCL‐2, and G‐CSF were shown to be expressed mainly by AM in the initial phase of infection (around 6 h post‐infection)." (PMID 29119707, 2018). "Levels of type I IFNs, TNF-α, IL-6 and CXCL1 as well as CCL2, and IFN-γ were all significantly higher in lungs of 6:2 Tky/05 virus infected mice than in the other three groups at day 2 post infection." (PMID 29300777, 2018). "We measured the levels of IL-1β, IL-6, MIP-1α, and CXCL1 in cerebellum and spleen, as well as of bioactive lipids in serum in PEA- and vehicle-treated animals 24 h after infection." (PMID 30505308, 2018). "Although mRNA levels of all these cytokines reduced in RV-infected mice with COPD phenotype, the levels of CXCL-1, CXCL-10, CCL3, TNF-α, IL-17A and IFN-γ remained high up to 14 days post-infection." (PMID 29975735, 2018). "The cytokines IL8, CXCL1, and CCL20 play important roles during the early phase of infection to attract different populations of immune cells and thus these were selected for measurements by ELISA." (PMID 30062089, 2018). "CXCL2 is highly homologous and shares many of the same roles in acute inflammation as CXCL1, including interaction with the CXCR2 receptor, secretion by monocytes and macrophages, and attraction of neutrophils to sites of infection and inflammation." (PMID 29661181, 2018). "IFN-alpha (IFN-α) was detected in the lungs of 6:2 Tky/05 virus-infected mice along with IL-6 at day 2, whereas levels of TNF-α, CXCL1, CCL2 and IFN-γ continued to rise through day 3 post infection." (PMID 29300777, 2018). "SpyCEP is a 170 kDa serine protease expressed on the surface of GAS, which proteolytically cleaves and abrogates the activities of the human chemokines CXCL1, CXCL2, CXCL6, and CXCL8/IL-8, impairing neutrophil recruitment to the site of infection." (PMID 29868516, 2018). "IFNg, IL6, KC (CXCL1) and LIX (CXCL5) were higher in the lungs of CB infected mice, indicating a heightened proinflammatory response in the CB infection." (PMID 28155887, 2017). "We next measured pro-inflammatory mediators in splenic tissue by ELISA and observed significant increases in IL-6, CXCL1(KC), IFN-γ, TNF-α, CCL2 (MCP-1), and MMP-3 levels after infection." (PMID 28874800, 2017). "TLR2 is induced during infection and is important for DC activation, which influences the drive of naïve CD4+ T cells to the Th1 and Th17 pattern as well as the production of CXCL1." (PMID 28280488, 2017). "CXCL1 (C-X-C motif ligand 1) has been shown to be upregulated by TLR/MyD88 activation and is important in corneal wound healing and infection Therefore, we examined the baseline expression of this chemokine in untreated mice deficient in MyD88 or IL-1R." (PMID 28796783, 2017). "This is followed by the production of neutrophil chemoattractant chemokines including CXCL1 and CXCL2 mainly produced by activated tissue residential macrophages, which in turn induce neutrophil recruitment to the site of infection." (PMID 28817707, 2017). "This early mucosal resistance phenotype was associated with an early increase of mucosal protein levels of IL-1β, IL-22, KC/CXCL1 and MCP-1 and elevated transcription rates of Cxcl1 and Nos2/iNos measured at 18 hours post infection." (PMID 28662171, 2017).
infection (continued). "Mechanistically, DCs are activated during infection in a TLR2-dependent manner, promoting prototypal Th1 and Th17 subsets and CXCL1 production." (PMID 28280488, 2017). "In this model, we also found that some genes exhibited a downward trend (e.g., Ptgs2, Rel, IL4r, CXCL1, CXCL2, TLR5, Nfatc3 and Egr2) in M. fortis after infection." (PMID 28900150, 2017). "Wild-type infection also induced IL-6, CCL2 (MCP-1), and CXCL1 at day 2 postinfection and suppressed IL-15 production compared to levels in mock-infected animals." (PMID 29138302, 2017). "Optimal expression of Ccl2, Ccl3, Ccl4, and Cxcl1 depends on DDR signaling in macrophages, and these chemokines regulate the migration of innate immune cells during infection." (PMID 28362262, 2017). "Infection activates a broad chemokine response to infection, including CXC (CXCL1, CXCL5, CXCL8, CXCL9, and CXCL10) and CC chemokines (CCL2, CCL3, and CCL5)." (PMID 26927188, 2016). "ELISA measurements confirmed a robust induction of CXCL1, G-CSF, and CCL2 in the peritoneal cavity of mice infected with E. coli 127 in comparison with infection with any of the other bacteria." (PMID 27713743, 2016). "Despite equivalent bacterial loads, infection with tonB K. pneumoniae resulted in increased bacterial dissemination and IL-6, CXCL1, and CXCL2 secretion compared to infection with the entB ybtS tonB mutant." (PMID 27624128, 2016). "Consistent with our in vivo findings of diminished CXCL1 in BAL from Nlpr12−/− mice following infection with F. tularensis LVS, we observed that Nlpr12−/− BMDM secreted significantly less CXCL1 in response to F. tularensis LVS, S. aureus and P. aeruginosa." (PMID 27779193, 2016). "Other chemokines, such as KC (CXCL1) and Rantes (CCL5), were also differentially expressed in A20AEC-KO and control A20WT mice at day 8 post-infection, although at lower levels." (PMID 26815999, 2016). "Both CXCL1 and CXCL-2 expression decreased in Pam3CSK4-pretreated mice at 6 and 12 h post infection." (PMID 26974438, 2016). "The local innate immune response of mammary glands was swiftly activated after S. aureus inoculation during the initial stage of infection, characterized by up-regulation of gene expression of TLR2, NOD2, TNF-α, IL-1β, IL-6, and CXCL1." (PMID 25990971, 2015). "The lungs of ECTV-infected Fas- and FasL-deficient mice showed significant inflammation during later phases of infection accompanied by decreased expression of anti-inflammatory IL-10 and TGF-β1 cytokines and disturbances in CXCL1 and CXCL9 expression." (PMID 25873756, 2015). "In this study, differences in TNF- α, CXCL1/KC, and lung histology were compared between CFTR–/– mice and WT-mice after 24 hours of infection with highly mucoid Sp strain CHB756." (PMID 26469863, 2015). "Our data clearly show an increased expression of a set of chemokines (CCL20, CCL5, CXCL1, CXCL10, CXCL11, CCL25) normally involved in H. pylori gastritis at both 6 and 18 weeks of infection in mice, which decreased after curcumin treatment." (PMID 25569625, 2015). "Of note, although the known neutrophil chemoattractants CXCL1 (KC) and CCL2 (MCP-1) increased following infection, the levels were similar in aged vs. young mice." (PMID 25595646, 2015). "In this study, IL-17 administration exacerbates neutrophil infiltration through the induction of CXCL1, CXCL2 and CXCL5 following S. aureus intramammary infection, whereas neutralization of the IL-17 by anti-IL-17 antibody reduced neutrophil infiltration." (PMID 26230498, 2015). "Levels of CXCL1/KC, IFN-γ, TNF-α, and IL-10 in the lung 1, 7, 15 and 30 days post-infection were significantly higher (approximately 30%, 40%, 19% and 36%, respectively) (p<0.05) in mice infected with the L27/01 strain, particularly 1 to 7 days post-infection." (PMID 25392951, 2014). "In contrast, we observed significantly less production of IL-12p40, IL-12p70, IL-1α, IL-1β, IL-17A, CXCL1, CCL2 and CCL5 in the lungs as the infection progressed." (PMID 25119981, 2014).